EIF4E (eukaryotic translation initiation factor 4E)
Diseases named in the same sentence as EIF4E in open-access papers (continued):
Sharing a sentence is not in itself a finding about the gene and the disease.
cancer (continued). "EIF4E, another gene mediator of the REACTOME_ TRANSLATION network, is an mRNA 5’ cap-binding protein that is involved in translation initiation, and its upregulation is involved in cancer development and progression." (PMID 32204397, 2020). "A very recent contribution demonstrates that in Asn-depleted cancer cells a translational reprogramming, dependent on the increase of MAPK-interacting kinase 1 (MNK1) and eukaryotic translation initiation factor 4E (eIF4E), promotes enhanced ATF4 translation and, hence, ASNS expression." (PMID 31998641, 2019). "The increase of phosphorylated eIF4E promotes EMT and metastasis in cancer." (PMID 31119584, 2019). "Further, five human cancer cell lines (SMMC7721, HepG2, MCF7, MDA-MB-231, and A549) were respectively treated with different concentrations of B591 for 5 h and eIF4E [nuc:cyto] ratios were determined by a high content assay using Thermo Scientific Cellomics ArrayScan VTI HCS." (PMID 30635656, 2019). "Because eIF4E phosphorylation resides at a convergent point between two predominant signaling pathways (mTOR and ERK signaling), the MKNK kinases play a critical role in the downstream translation initiation of pro-cancer mRNA." (PMID 29568395, 2018). "We show here that prolonged treatment with asTORi strongly augments infection of HSV1-dICP0 in cancer cells, but not in normal cells, an effect modulated via eIF4E/4E-BP expression." (PMID 30138450, 2018). "EIF4E is phosphorylated by MKNK1/2, which are downstream of the RAS/RAF/MEK/ERK and p38 signaling pathways, and is a major cap-binding protein involved in the regulation of mRNA translation in normal and cancer development." (PMID 29188469, 2018). "In this study, we showed that ITGB3 is translationally activated upon hypoxia and hypoxia + PP242 in cancer and non-tumourigenic breast epithelial cells and that this protein synthesis activation was dependent on eIF4E." (PMID 29383126, 2017). "As eIF4E has been reported to play an important role in EMT and cancer metastasis, we suspected that it might be a downstream target of AEG‐1 and may mediate the oncogenic effect of AEG‐1." (PMID 28661037, 2017). "Our results also demonstrate that cIAP1 alone is not enough to control the levels of eIF4E to prevent cancer cell growth and, therefore, cIAP1 and CHIP collaboration is required for proper control of eIF4E and prevention of tumorigenesis." (PMID 28852129, 2017). "Among these proteins, six are reportedly related to cell survival and death; i.e., RhoGDI, GRP78, TXNDC5, COMD9, EIF4E, and PRDX3, which reportedly affect Rho GTPase activity, ER stress, cancer progression, NF-κB suppression, cell growth, cell cycle progression, and apoptosis." (PMID 27428937, 2016). "Similarly, eIF4E, VEGF-C, and MMP-2 promoted and E-cadherin suppressed the lung metastasis of cancer cells." (PMID 27907907, 2016). "In contrast to EIF4E, EIF3A has been reported to be upregulated in various cancers but plays different roles in carcinogenesis: acts as tumor suppressor in squamous cell carcinomas and is correlated with better survival, and acts as tumor promoter in other epithelial carcinomas." (PMID 25658620, 2015). "Phospho-eIF4E (p-eIF4E), unlike eIF4E that is essential for survival and growth of normal cells, is specifically required by cancer cells including AML cells." (PMID 25915158, 2015). "Therefore, the roles of the interaction and expression of eIF4E and 4E-BP1 in cancer progression has been widely examined." (PMID 26204490, 2015). "The Epstein-Barr virus has been associated with the development of cancer and, unlike EV71, induces eIF4E overexpression." (PMID 25690796, 2015). "As phospho-eIF4E (p-eIF4E), unlike total eIF4E (t-eIF4E) essential for normal cells, is specifically required by cancer cells, it is an attractive, yet unrealized, target for anti-tumor intervention." (PMID 25915158, 2015). "Overexpression of eIF4E has been found in many types of tumors and cancer cell lines, but not in typical benign lesions." (PMID 24551240, 2014).
cancer (continued). "Recent findings suggested that eIF4E is a key determinant of PI3K/Akt/mTOR- and Ras/Raf/MAPK-mediated tumorigenic activity, and that targeting eIF4E should have a major impact on these pathways in human cancers." (PMID 25277198, 2014). "Our data support the notion that agents which degrade Mnk and block eIF4E mediated downstream events are likely to be superior to selective small molecule Mnk inhibitors such as cercosporamide and CGP57380 in the treatment of human cancers." (PMID 24504069, 2014). "Preclinical use of this 4EASO elicited single agent activity in human cancer xenografts (breast, prostate), decreasing eIF4E expression and diminishing tumor growth without toxicity." (PMID 24260583, 2013). "In experimental models of cancer forced expression of eIF4E, of a constitutively active but non-phosphorylatable mutant of eIF2α (eIF2α-S51A) or of initiator Met-tRNAi transforms immortalized fibroblasts." (PMID 22935625, 2012). "Recent findings suggest that eIF4E activity is a key determinant of the PI3K/Akt/mTOR and Ras/Raf/MEK/ERK mediated tumorigenic activity and targeting eIF4E should have a major impact on these pathways in human cancer." (PMID 22392765, 2012). "Surprisingly, non-transformed cell lines were not less sensitive to rapamycin and did not have lower eIF4E activities than cancer lines, suggesting the mTOR/4E-BP1/eIF4E axis is deregulated in these non-transformed cells." (PMID 21320304, 2011). "Estimates of eIF4E activity in cancer biopsies taken at diagnosis did not predict sensitivity to 11-14 days of pre-operative everolimus treatment, as assessed by change in tumour cell proliferation from diagnosis to surgical excision." (PMID 21320304, 2011). "Expression of eIF4E in cancer has been studied extensively, however, expression does not equate to activity; therefore, interpretation of its influence is more complex than simply assessing expression." (PMID 19367274, 2009). "Given that both normal and cancer cells express eIF4E, it is important to develop therapeutic strategies that target cancer cells without harming normal cells." (PMID 20049173, 2009). "The eIF4E pathway is a target for cancer therapy with drugs that either inhibit eIF4E activity indirectly (mTOR inhibitors that reduce 4E-BP1 phosphorylation thereby inhibiting eIF4E), or directly (by binding to/reducing expression of eIF4E)." (PMID 19367274, 2009). "Since many cancers overwhelm the inhibitory capacity of 4E-BP1 by downregulating 4E-BP1 and/or upregulating eIF4E, the finding that SMAPs increase 4E-BP1 levels points to the promise of these agents for restoring the 4E-BP1/eIF4E ratio for translational control in a broad spectrum of cancer types." (PMID 39869680, 2025). "Also, elevated eIF4E correlated with radioresistance, and selective silencing of eIF4E augmented radiosensitivity of cancer cell lines but not normal cells." (PMID 41498028, 2025). "Thus, activated MNK/eIF4E induced the activation of Wnt/β-catenin in cancer, but not in normal cervical cells, through an increase in eIF4E overexpression and phosphorylation, which promoted growth and migration." (PMID 32340135, 2020). "However, the second gene, eukaryotic translation initiation factor 4E (EIF4E), is activated in cancers and is required for translation of some mRNAs involved in proliferation and survival, as well as in EMT process and cancer invasion." (PMID 31010087, 2019). "Total eIF4E activity is required for proliferation of both tumor and normal cells, whereas phosphorylated eIF4E is not essential for normal cell proliferation and survival, but is specifically required for cancer cells." (PMID 30388805, 2018).
cancer (continued). "However, loss of 4E-BP1 expression with an increase in free eIF4E, rather than the phosphorylation status of 4E-BP1, is considered to be a primary determinant for cancer cell resistance to mTORkis12,13." (PMID 29263324, 2017). "Thus, we reasoned that small molecules that directly target the p-eIF4E but not eIF4E would exhibit more potent and safer therapeutic effects for cancer." (PMID 25915158, 2015). "Moreover, eIF4E is a key event downstream of ras and phosphatidylinositol 3-kinase/protein kinase B/mammalian target of rapamycin (PI3K/AKT/mTOR) signaling pathway, which are frequently activated in a diverse range of human cancer." (PMID 26078354, 2015). "In the present study, we demonstrate that human and canine cancer cell lines express constitutively activated class I PI3K/Akt/mTORC1 axis signaling, as evidenced by detectable levels of phosphorylated forms of PI3K downstream effectors, including Akt, mTOR, S6RP, 4EBP1 and eIF4E." (PMID 22647622, 2012). "However, BP1−/− and BP1−/− BP2−/− mice do not develop cancers more readily than controls, highlighting the importance of redundancy of regulators in the control of eIF4E." (PMID 20049173, 2009). "By further examining changes in the PI3K/AKT/mTOR pathway looking at the downstream transcription factors S6K and eIF4E, and PRAS40 (inhibits mTOR and IRS-1), we could identify their role in the negative feedback of the PI3K pathway, an effect commonly seen in various cancers and cancer models." (PMID 37908840, 2023). "However, considering what is found in cancer models, this negative feedback is not activated in early-stage disease, permitting eIF4E and S6K to act on the downstream regulators of mesenchymal cell transition, apoptosis, autophagy, senescence, cell growth, and motility." (PMID 37908840, 2023). "However, more regulator genes negatively related to those compounds, like AGO2, DCP2, EIF3D, EIF4E, LARP1, and NCBP3 (related to 30 cancer drugs both in GDSC and CTRP), indicating the patients with higher mRNA expression level of these regulator genes might sensitive to these compounds." (PMID 36092891, 2022). "Our results demonstrated that silencing of NONO reduced the protein levels of eIF4E and RACK1, suggesting that NONO may have a role in regulating the protein translation process in cancer cells." (PMID 37370134, 2023). "Finally, despite robust activities in blocking eIF4E phosphorylation at S209, none of the 2 MNK1/2 inhibitors exhibited notable tumor-inhibiting activities in any of the tumor cell lines we tested, including the MAPK4-low and MAPK4-KO cancer cell lines." (PMID 37531320, 2023). "With the combined inhibition of CDK9-mediated transcription and Mnk-eIF4E translation, together with its low toxicity in non-transformed cells and favourable pharmacological properties manifested, CDKI-73 may offer an opportunity to treat a wide range of human cancers." (PMID 25277198, 2014).
tumor (334 papers, 1998 to 2026). "We discovered that expression of the gene encoding the nuclear export protein XPO1, which shuttles eIF4E to the cytoplasm, was substantially elevated in NB tumor cell populations and that upregulated XPO1 expression correlated with poor patient survival." (PMID 41279557, 2025). "Other PCa oncogenic events, such as loss of Pdcd4 or activation of the MNK/eIF4E pathways, have been described to impact cell secretome protein composition affecting and promoting immune evasion and tumor progression." (PMID 40268923, 2025). "This agrees with studies indicating that eIF4E promotes translation of highly structured, growth-promoting mRNAs linked to cellular transformation and tumor progression." (PMID 41308988, 2025). "Dephosphorylated 4EBP1 associates with eIF4E and inhibits binding between eIF4E and eIF4G, resulting in reduced translation of mRNAs that are essential to cell proliferation for tumor." (PMID 38954773, 2024). "eIF4E expression and activation are linked to cell transformation and the tumour starts as a proto‐oncogene." (PMID 38071502, 2024). "Many studies have reported that overexpression of eIF4E is associated with poor prognosis in cancer patients and can lead to tumor vascularization and invasion." (PMID 36830614, 2023). "The mitogen-activated protein (MAP) kinase-interacting kinase 1/2 (MNK1/2)–eukaryotic initiation factor 4E (eIF4E) pathway, which is associated with tumor cell proliferation and metastasis, is also regulated by cytokines." (PMID 39171279, 2023). "Elevated levels of p-MNK1 and p-eIF4E correlate with tumor grade and with an increase in Cyclin D1 expression, which is associated with tumor recurrence, increased tumor size, and poor prognosis." (PMID 36994107, 2023). "The overexpression of eIF4E precisely elevates the translation of mRNAs associated with tumor growth and invasion, making it an important target for tumor therapy." (PMID 37601696, 2023). "Our analysis of TCGA clinicopathological data showed that high eIF4E expression in BC was significantly associated with tumor lymph node metastasis." (PMID 37217473, 2023). "The m7GRGs AGO2, EIF4E3, DCPS and EIF4E have been extensively studied, and some of them have been associated with tumour progression." (PMID 37353728, 2023). "More specifically, the overexpression of eIF4E and an increase in its phosphorylation correlates with higher tumor grade and is associated with poorer prognosis." (PMID 35267591, 2022). "As a proto-oncogene, the expression and activation of eIF4E are associated with cell transformation and tumor initiation." (PMID 34876062, 2021). "Immune infiltration analysis showed that the eIF4E expression level was significantly associated with the tumor purity and immune infiltration levels of different immune cells in BRCA." (PMID 34876062, 2021). "Even a modest increase in eIF4E expression was sufficient to cause cellular transformation, while expression of a non-phosphorylatable eIF4E mutant in mice resulted in delayed tumor development and metastasis." (PMID 32731503, 2020). "By contrast, a reciprocal phosphomimetic serine to aspartic acid mutation induced accelerated tumor onset which is comparable to that of wild type eIF4E." (PMID 33148274, 2020). "Cytokine profiling revealed a pro-MDSC cytokine signature in the eIF4EWT tumor, indicating a phosphorylated eIF4E-linked immunosuppression." (PMID 32731503, 2020). "Results indicated that higher expression levels of eIF4E and p-4EBP-1 were associated with the risk for tumor recurrence, with hazard ratios of 4.1 (P = 0.011) and 16.6 (P = 0.001), respectively." (PMID 31756179, 2019). "As a key element of the initiation translation complex, eIF4E participates in the translation of tumor–associated proteins, such as c‐MYC, cyclin D1, and MCL‐1 (Kosciuczuk, Saleiro, & Platanias, 2017)." (PMID 30891950, 2019).
tumor (continued). "Overexpression of eIF4E has been reported in advanced tumor stages, and also to be associated with decreased rates of patient survival." (PMID 30761182, 2019). "The expression level of eIF4E and p-4EBP1 were significantly associated with tumor recurrence and recurrence-free survival." (PMID 31756179, 2019). "We further found that a higher expression level of p-eIF4E showed a weak association with tumor recurrence, with a hazard ratio of 0.173 (P ≤ 0.001)." (PMID 31756179, 2019). "Cytoplasmic expression of eIF4E showed a statistically significant association with tumor grade (P < 0.001)." (PMID 27440383, 2016). "Tumour growth was associated with decreases in mTOR and p70S6K1 gene expression, as well as reduced expression of eIF4E, eIF5 and eIF2a, three factors involved in protein synthesis (the tumour effect was highly significant at P < 0.05)." (PMID 26847205, 2016). "Elevated eIF4E expression has been documented in many tumor tissues, and is associated with aggressiveness and poor outcome of patients." (PMID 27276678, 2016). "eIF4E is a presumptive oncogene and is frequently elevated in tumor cells with an association with a poor prognosis." (PMID 23599772, 2013). "High levels of eIF4E are able to confer resistance to apoptosis in cells exposed to a variety of death stimuli, and eIF4E activity is regulated by the anti-apoptotic protein kinase Akt, an enzyme implicated in tumour cell survival and resistance to therapy." (PMID 23940704, 2013). "Histologically tumor-free margin with high expression of eIF4E has a seven-fold risk of local failure." (PMID 21513566, 2011). "A significant positive association between eIF4E immunoreactivity and the histological grade of the invasive tumor was found (p = 0.016)." (PMID 17010208, 2006). "This is supported by clinical observations that dysregulation of the eIF4E pathway is associated with tumour progression." (PMID 16953237, 2006). "Using linear regression analysis, we studied the association of the percentage of tumor cells staining positive for eIF4E and MVD." (PMID 17010208, 2006). "In superficial tumours (n = 37) high expression of eIF-4E was associated with a poor prognosis and reduced stage progression-free survival (P = 0.04, Cox proportional hazards model)." (PMID 10638984, 2000). "Based on this, we hypothesized that PBK may regulate the expression and activity of EIF4E, suggesting that the PBK/EIF4E pathway is likely to be an important tumor-associated pathway." (PMID 39649886, 2024). "Furthermore, increased eIF4E phosphorylation is associated with a higher tumor grade, early disease onset and worse prognosis." (PMID 32340135, 2020). "However, in MDA-MB-231 and PDX tumors in vivo, racemate appears to be more effective than the two enantiomers in inhibiting the tumor growth, volume and Mnk-eIF4E signaling associated proteins." (PMID 30832411, 2019). "In the xenograft study, gemcitabine plus rad001 showed the best therapeutic effect on tumor volume change, and was associated with increased caspase-3 expression, decreased eIF4E expression, as well as overexpression of both death receptor- and mitochondrial apoptotic pathway-related genes." (PMID 29666220, 2018). "eIF4E is a transcriptional target of c-Myc; interestingly, overexpression of eIF4E has been observed to cause malignant transformation of human epithelial cells and fibroblasts and promote tumor formation in transgenic mice." (PMID 25690796, 2015). "Eukaryotic translation initiation factor 4E (eIF4E), a proto-oncogene, is important in translational regulation and its overexpression selectively increases the mRNA translation of proteins associated with tumor growth, invasion and metastasis." (PMID 25435943, 2015).